NOTCH4 (notch receptor 4)
Diseases named in the same sentence as NOTCH4 in open-access papers (continued):
Sharing a sentence is not in itself a finding about the gene and the disease.
lung adenocarcinoma (6 papers, 2018 to 2024). A carcinoma that arises from the lung and is characterized by the presence of malignant glandular epithelial cells. "In addition, 643 genes were differentially expressed in lung adenocarcinoma tissue versus normal tissue with predominant downregulation of vasculogenesis-associated genes such as NOTCH4 and TBFBR3." (PMID 29769567, 2018). "In lung adenocarcinoma, high expression of NOTCH4 and C-X-C chemokine receptor 4 is predictive of poor prognosis." (PMID 39595659, 2024). "We found that in lung adenocarcinoma, compared with NOTCH4-WT patients (ORR = 21.2%), NOTCH4-MUT patients (ORR = 25.0%) tended to have a better response to ICI treatment." (PMID 34284787, 2021). "In addition, STAT3 inhibitors currently being tested in clinical trials should be used with caution, at least in tumors in which the NOTCH4 pathway and thus HES1 play a protumorigenic role, as in lung adenocarcinoma." (PMID 37268635, 2023). "Here, we have performed immunohistochemistry staining of Notch4 in the lung adenocarcinoma tissues and adjacent non-malignant lung tissues from lung adenocarcinoma patients." (PMID 34988077, 2021).
lung carcinoma (6 papers, 2013 to 2024). "Anti-Notch4 treatment significantly delayed tumor growth in mouse models of breast, skin, and lung cancers." (PMID 38984877, 2024). "This study demonstrated that TCF21 and Notch4 were greatly down-regulated in lung cancer cells and TAMs, and Notch4 was the downstream target gene of TCF21." (PMID 37765264, 2023). "Here we report that Notch4 is upregulated in lung tissue from lung cancer patients." (PMID 34988077, 2021). "However, the role of Notch4 as an oncogene in lung cancer under hypoxia has not been clarified." (PMID 34988077, 2021).
mammary adenocarcinoma (6 papers, 2009 to 2022). "Consistent with our finding that Notch4 is expressed in the tumor vasculature, the Notch ligand Dll4 is detected in the vessels of infiltrating human breast adenocarcinoma samples, making it a possible ligand for Notch4 in tumor vasculature." (PMID 23601498, 2013). "It was discovered that the Notch4 locus is a common integration site for MMTV and the constitutive ligand-independent activation of Notch4 leads to a greater activation of its target genes and a higher risk of onset of mammary adenocarcinoma." (PMID 35682974, 2022). "It was found that the Notch 4, one of the four Notch receptors, is involved in the constitutive ligand-independent activation of Notch 4, and could facilitate the development of mammary adenocarcinoma." (PMID 34944829, 2021). "Mice infected with MMTV (mouse mammary tumor virus) resulted in a hot spot insertion in the Notch 4 locus, which led to the constitutive expression of NOTCH-4 and its target genes, truncation and activation of NOTCH-1 as an oncogene, and eventual development of mammary adenocarcinoma." (PMID 36476410, 2022). "Accordingly, a recent study demonstrates that activation of different Notch receptors in the human mammary adenocarcinoma cell line MDA-MB-231 drives dramatically opposing effects, leading to either increased apoptosis in the case of Notch2 or increased proliferation in the case of Notch4." (PMID 20011512, 2009).
pancreatic cancer (6 papers, 2011 to 2024). "We performed independent evaluations of the impacts of Notch1 or Notch4 loss in the context of previously established GEMMs for pancreatic cancer, LSL-KrasG12D;p48-Cre and p16fl/fl;LSL-KrasG12D;p48-Cre GEMMs." (PMID 36970723, 2022). "It is possible that the loss of Notch4 first modified the stroma, which consequently hindered pancreatic tumor development and progression in Notch4-null mice." (PMID 36970723, 2022). "Notably, the downregulation of NOTCH4 is linked to breast and pancreatic cancer, suggesting cancer-associated roles of axon guidance molecules in lung carcinogenesis." (PMID 37513116, 2023). "Using immunohistochemistry (IHC) on a tissue array, we discovered that Notch3 was most often overexpressed in pancreas cancer, followed by Notch4." (PMID 22074495, 2011). "Using a pancreas cancer tissue microarray, we noted that Jagged1, Notch3 and Notch4 are overexpressed in pancreas tumors (26%, 84% and 31% respectively), whereas Notch1 is expressed in blood vessels." (PMID 22074495, 2011). "Additionally, altered BCAA metabolism in pancreatic cancer has been linked with upregulated levels of NOTCH3 and NOTCH4, suggesting their involvement in metabolic adaptations seen in this disease." (PMID 39286249, 2024). "Unbiased RNA-seq analyses comparing pancreatic tumor cell lines derived from the pancreatic tumors of the PKC versus the N4−/−PKC mice led to the identification of Pcsk5 as a potential downstream mediator of Notch4 signaling." (PMID 36970723, 2022). "Therefore, in this study, we investigated the contributions of Notch1 and Notch4 to the development of pancreatic cancer in vivo." (PMID 36970723, 2022). "Our data also give hope that a Notch4-specific inhibitor (which would induce global inhibition of Notch4 in tissues) may have therapeutic value in suppressing pancreatic cancer growth." (PMID 36970723, 2022). "However, both Notch1 and Notch4 have also been described to be highly re-expressed in pancreatic cancer and cholangiocarcinomas." (PMID 33498866, 2021). "In contrast, the role of Notch4 in pancreatic cancer is largely unknown." (PMID 36970723, 2022). "To understand the role of Notch4 in pancreatic tumorigenesis further, we examined the expression levels of Notch4-ICD in the pancreatic tumors developed in the PKC GEMM by IHC and IF." (PMID 36970723, 2022). "To delineate potential pathways whereby the inactivation of Notch4 leads to preferable outcome in PDAC, we performed RNA-seq analysis between primary pancreatic cancer cell lines established from the pancreatic tumors developed in the PKC and the N4−/−PKC GEMMs." (PMID 36970723, 2022). "RNA-sequencing analysis of pancreatic tumor cell lines derived from the PKC and N4−/−PKC GEMMs revealed that 408 genes were differentially expressed (FDR < 0.05) and Pcsk5 is a potential downstream effector of the Notch4 signaling pathway (P < 0.001)." (PMID 36970723, 2022).
Alzheimer disease (5 papers, 2015 to 2021). A progressive, neurodegenerative disease characterized by loss of function and death of nerve cells in several areas of the brain leading to loss of cognitive function such as memory and language. "Genetic variants in NOTCH3 gene have been shown to be associated with cerebral small vessel disease, while NOTCH4 variants linked to Alzheimer's disease." (PMID 34257585, 2021). "Genetic variants of Notch3 and Notch4 genes are associated with cerebral small vessel disease 27 and Alzheimer's Disease 28, respectively." (PMID 28568708, 2017). "In addition, changes in LRP1 may have roles in dementia and Alzheimer’s disease (AD) progression, as does NOTCH4." (PMID 31026304, 2019). "Furthermore, NOTCH4 may play important roles in the pathogenesis of Alzheimer disease in the Japanese population and in the United Kingdom population." (PMID 26253105, 2015).
migraine (5 papers, 2013 to 2023). "In migraine, there is evidence that distinct polymorphisms of NOTCH4 gene significantly modify clinical characteristics of migraine phenotype." (PMID 36797674, 2023). "Intriguingly, we found that genetic variants within NOTCH4, a gene involved in vascular maintenance and remodeling, significantly influence several clinical features of migraine." (PMID 23566281, 2013). "It is unlikely that genetic variations within the NOTCH4 gene contribute greatly to migraine susceptibility." (PMID 23566281, 2013). "The aim of this study was to test the hypothesis that polymorphisms of the NOTCH4 gene would modify the occurrence and the clinical features of migraine." (PMID 23566281, 2013). "The aim of the present work was to evaluate the association between migraine and the NOTCH4 gene." (PMID 23566281, 2013). "Thus, the NOTCH4 gene may increase the risk of migraine and cognitive dysfunction, and the TSBP1-AS1 gene may increase the risk of cognitive dysfunction." (PMID 35783123, 2022). "Our data support a role for NOTCH4 as a disease-modifier gene in migraine." (PMID 23566281, 2013). "Our study shows that genetic variations within the NOTCH4 gene significantly modify the clinical characteristics of migraine and may have a role in disease pathogenesis." (PMID 23566281, 2013). "In addition, we assessed the relation between different NOTCH4 genotypes and the clinical characteristics of migraine." (PMID 23566281, 2013). "Finally, we can hypothesize that the NOTCH4 gene may be particularly involved in some migraine subtypes." (PMID 23566281, 2013). "Finally, we compared the clinical characteristics (age of onset, duration of the disease, frequency of migraine as attacks for year, photophobia, phonophobia, nausea, vomiting, menstrual migraine, and variation at menarche) of our migraine patients according to different NOTCH4 genotypes." (PMID 23566281, 2013). "NOTCH4 gene is located at 6p21.3, in the major histocompatibility complex (MHC), a chromosomal region intensively investigated in migraine." (PMID 23566281, 2013).
systemic sclerosis (5 papers, 2012 to 2024). A chronic disorder, possibly autoimmune, marked by excessive production of collagen which results in hardening and thickening of body tissues. "The polymorphism in NOTCH4 (rs443198 and rs9296015) gene has been associated with systemic sclerosis." (PMID 34258301, 2021). "NOTCH4 has also been associated with neonatal lupus, multiple sclerosis, systemic sclerosis, and other immune-related disorders." (PMID 22952805, 2012). "rs443198 is mapped to gene NOTCH4 which is associated with systemic sclerosis (M34)." (PMID 38728360, 2024). "Moreover, a missense mutation in the NOTCH4 gene (chromosome 6p21 locus, c.4245G > A: p.Met1415Ile) was identified by a family-based whole exosome sequencing study and was linked to the pathogenesis and development of systemic sclerosis in this family." (PMID 34258301, 2021).
bipolar disorder (4 papers, 2009 to 2022). A disorder of the brain that causes unusual shifts in mood, energy, activity levels and the ability to carry out day-to-day tasks. "The only pleiotropic gene on chromosome 6 was NOTCH 4, which has recently also been implicated in bipolar disorder." (PMID 23637625, 2013).
bladder cancer (4 papers, 2021 to 2025). "A recent study reported that NOTCH4 mutation is a novel biomarker associated with better response to immune checkpoint inhibitor therapy in a variety of cancers, including bladder cancer." (PMID 36769068, 2023). "Although recent data increased our knowledge about NOTCH 4, new efforts are still required to better explore the role of this receptor in bladder cancer." (PMID 41008920, 2025). "NOTCH1, NOTCH2 and NOTCH4 were significantly downregulated in bladder cancer samples compared with controls." (PMID 37728427, 2023).
brain arteriovenous malformations (4 papers, 2012 to 2023). "While NOTCH3 signaling in regulating vascular smooth muscle cell differentiation has been widely reported, a possible role of NOTCH4 in contributing to the pathogenesis of brain arteriovenous malformations has been described only in mice." (PMID 37063679, 2023). "Expression of constitutively active Notch4 (int3) in the mouse endothelium develops features of brain arteriovenous malformations characterized by cerebral arteriovenous shunting and vessel enlargement." (PMID 22187650, 2012).
colon carcinoma (4 papers, 2016 to 2025). "On the other hand, CIC, DST, KAT6B and NOTCH4 represent novel genes that may be implicated in the onset and/or development of colon cancer." (PMID 29844865, 2018). "In addition, miR-34a has an inhibitory effect on NOTCH1, NOTCH2, and NOTCH4 expression in pancreatic ductal carcinoma, whereas, in colon carcinoma, its inhibition rescued the expression of NOTCH1, NOTCH2, and BCL2." (PMID 40149537, 2025). "On the other hand, CIC, DST, KAT6B and NOTCH4 have not been previously implicated in the development of colon cancer, and for this reason, deserve further studies." (PMID 29844865, 2018). "mRNA expression levels of NOTCH-1, NOTCH-3, NOTCH-4, JAG-1, DLL-4, Hes-1, and Hey-1 were quantified to elucidate the action of endostatin/CTX on the notch signaling pathway in colon cancer." (PMID 26762567, 2016).
lymph node metastasis (4 papers, 2018 to 2023). "In patients with oral squamous cell carcinoma, the high expression of Notch4 is correlated with poor differentiation, advanced clinical stage, periosteal invasion and lymph node metastasis." (PMID 37108670, 2023).
Obesity (4 papers, 2015 to 2025). Accumulation of substantial excess body fat. "Another study of DNA methylation in whole blood and the association with obesity observed the association between DNA methylation changes of Ddah2, Cux1, Notch4, and Dst with BMI." (PMID 35458198, 2022). "It would be very interesting to determine the methylation status of Notch4 in cardiovascular disease and other common underlying conditions such as hypertension or obesity." (PMID 25921777, 2015). "By contrast, although the human orthologs of glp-1, NOTCH4 and EYS, were associated with obesity in GWAS, they have not been causally linked to the disease." (PMID 34492009, 2021).
osteosarcoma (4 papers, 2009 to 2021). A usually aggressive malignant bone-forming mesenchymal neoplasm, predominantly affecting adolescents and young adults. "Moreover, Jag2 and Notch4 are highly expressed in some murine osteosarcomas, and NOTCH3 has somatic copy-number alterations in about 10% of human osteosarcoma samples." (PMID 34439353, 2021). "We have previously shown that the osteosarcoma cell line K7M2 actively expresses Notch genes (Notch1, Notch2, and Notch4; Hes1), but not Notch3." (PMID 27378829, 2016).
ovarian carcinoma (4 papers, 2017 to 2022). A malignant neoplasm originating from the surface ovarian epithelium. "In addition, Notch 4 mRNA high expression was associated with favorite OS in grade III ovarian cancer patients, HR 0.76 (0.64–0.9), p = 0.0018." (PMID 28415574, 2017). "Ovarian cancer cells express Notch1, Notch2, Notch3, Notch4 and Jagged2, while ECs located in the ovary express Jagged1 and Dll1 and Dll4 ligands." (PMID 36430649, 2022). "Notch4 mRNA high expression was significantly correlated to favorite OS for all ovarian cancer patients, HR 0.87 (0.76–1), p = 0.043." (PMID 28415574, 2017). "However, Notch4 mRNA high expression was significantly correlated to favorite OS for all ovarian cancer patients, HR 0.87 (0.76–1), p = 0.043." (PMID 28415574, 2017). "Notch4 was excluded because its expression was very low in ovarian cancer cell lines (data not shown)." (PMID 29423060, 2018). "Notch4 mRNA high expression was not significantly correlated to PFS for all ovarian cancer patients." (PMID 28415574, 2017). "Notch4 mRNA high expression was not significantly correlated to PFS for all ovarian cancer patients, HR0.89 (0.78–1.02), p = 0.091." (PMID 28415574, 2017). "Notch4 mRNA high expression was not correlated to PPS in ovarian cancer patients, HR 0.94 (0.79–1.13), p = 0.51." (PMID 28415574, 2017). "We found that Notch4 mRNA high expression was not significantly correlated to PFS for all ovarian cancer patients." (PMID 28415574, 2017). "Notch4 mRNA high expression was significantly correlated with favorite OS, but not PFS and PPS for all ovarian cancer patients." (PMID 28415574, 2017).
atherosclerosis (3 papers, 2022 to 2025). A disease characterized by the build-up of fatty material and calcium deposition in the arterial wall resulting in partial or complete occlusion of the arterial lumen. "Disturbed flow-activated JAG1-NOTCH4 promotes vascular dysfunction and EndMT-like programs in atherosclerosis, indicating that Notch1 and Notch4 are context-dependent regulators of endothelial fate." (PMID 41373869, 2025). "Light-sheet imaging revealed enrichment of JAG1 and NOTCH4 in EC of atherosclerotic plaques, and EC-specific genetic deletion of Jag1 (Jag1ECKO) demonstrated that Jag1 promotes atherosclerosis at sites of disturbed flow." (PMID 36044575, 2022). "The corollary is that therapeutic targeting of endothelial JAG1/NOTCH4 signaling in EC may provide a novel treatment strategy to prevent or treat atherosclerosis." (PMID 36044575, 2022). "Analysis of diseased arteries from hypercholesterolemic apolipoprotein E (ApoE)−/− mice using immunofluorescent light-sheet imaging revealed that JAG1 and NOTCH4 were enriched in regions of atherosclerotic plaque compared to adjacent nonplaque areas, indicating a potential role in atherosclerosis." (PMID 36044575, 2022).
liver cancer (3 papers, 2015 to 2024). An epithelial or non-epithelial malignant neoplasm that arises from the liver. "For example, Notch3 and Notch4 are highly expressed in primary liver cancer while they rarely present in regular liver." (PMID 32014047, 2020). "Notch4 expression is limited to vascular ECs hence Targeting Notch (especially 3 and 4) signaling could be an anti-angiocrine strategy in liver cancer." (PMID 32014047, 2020).
multiple sclerosis (3 papers, 2012 to 2022). A progressive autoimmune disorder affecting the central nervous system resulting in demyelination. "The SNPs near the HLA (NOTCH4; LOC101929163) region demonstrated association between essential hypertension and multiple sclerosis, with opposite direction of genetic effect." (PMID 35701404, 2022). "Similarly, there are 9 SNPs that were identified near rs9273532 locus (LOC101929163/NOTCH4 region) in the UK Biobank, which are in high LD, have opposite directions of effect on essential hypertension and multiple sclerosis, which also has not been characterized before in the GWAS catalog." (PMID 35701404, 2022).
pulmonary fibrosis (3 papers, 2011 to 2024). Chronic progressive interstitial lung disorder characterized by the replacement of the lung tissue by connective tissue, leading to progressive dyspnea, respiratory failure, or right heart failure. "Interestingly, NOTCH4 has been implicated in the pathways by which TGF-β induces pulmonary fibrosis, one of the most severe clinical manifestations of SSc." (PMID 21779181, 2011). "In murine pulmonary fibrosis, activation of Dll4/Notch4/CBF1 signaling intensifies interstitial transformation by impeding endothelial cell proliferation." (PMID 39450276, 2024). "Notch4 exacerbates pulmonary fibrosis by modulating pulmonary vascular endothelial cell differentiation and proliferation, leading to disrupted angiogenesis and lung tissue remodeling." (PMID 39450276, 2024). "Therefore, elucidating changes in Notch 1 and Notch 4 signaling pathways in lung fibrosis, and their correlation with EndoMT, is crucial for halting further abnormal transdifferentiation and fibrotic lung disease progression, while preserving normal tissue remodeling." (PMID 39450276, 2024).
vascular malformation (3 papers, 2013 to 2018). A non-neoplastic disorder that is the result of defects of vascular morphogenesis. "Collectively, these data suggest a link between the misexpression of Notch family members and NOTCH1 and NOTCH4 activation in human extracranial vascular malformations of all types." (PMID 30573741, 2018). "Similarly, Notch 4 labelling was also increased in vascular malformations and was confirmed by western blot analysis." (PMID 25846406, 2015). "Our data suggest that activation of Notch, including Notch4, signalling may contribute to vascular malformations not only in mice during development but also in adult brain in human." (PMID 24373503, 2013).